MT-RNR1 (mitochondrially encoded 12S rRNA)
Diseases named in the same sentence as MT-RNR1 in open-access papers (continued):
Sharing a sentence is not in itself a finding about the gene and the disease.
gastric cancer (1 paper, 2022). A primary or metastatic malignant neoplasm involving the stomach. "Another study indicated that MT-RNR1 mutations (652G insertion and 716G) were identified only in gastric cancerous tissues, especially in intestinal type gastric cancer, suggesting MT-RNR1 mutations were correlated with incidence of intestinal type gastric cancer." (PMID 35163579, 2022).
hearing (1 paper, 2015). "In order to study the prevalence of mutations in MT-RNR1 and MT-RNR2 genes among Finnish children, we studied a ten-year cohort of hearing impaired children born in Northern Finland." (PMID 25650108, 2015).
Intellectual disability (1 paper, 2018). "Genetic screening revealed a novel association of the LHON m.3460G > A primary mutation with the m.T961delT + C(n)ins within the mitochondrial encoded 12S RNA (MTRNR1) gene which segregates with the intellectual disability through the maternal branch of the family." (PMID 30053855, 2018).
Neonatal sepsis (1 paper, 2023). Systemic inflammatory response to infection in newborn babies. "In the UK, point of care genomic testing for mtRNR1 has been initiated prior to aminoglycoside use in neonatal sepsis, and NICE is expected to shortly release guidelines recommending CYP2C19 testing to guide choice of therapeutics after stoke." (PMID 37810217, 2023).
ototoxicity (1 paper, 2022). damage to the ear, specifically the cochlea or auditory nerve as a result of some toxic stimulus, eg from a drug. "The polymorphisms in the MT-RNR1 and MT-RNR2 genes were associated with increased mitochondrial and clinical adverse effects, most commonly ototoxicity and peripheral neuropathy." (PMID 34980117, 2022).
cancer (7 papers, 2014 to 2025). A tumor composed of atypical neoplastic, often pleomorphic cells that invade other tissues. "In summary, the CAR-mRNA design was stepwise optimized by the incorporation of CleanCap as 5′ cap analog, hAG 5′ UTR and AES/mtRNR1 3′ UTRs as well as m1ψ modification, which achieved a detectable CAR expression on cancer patients’ T cells for at least four days." (PMID 39940734, 2025).
infection (1 paper, 2023). The state of being infected such as from the introduction of a foreign agent such as serum, vaccine, antigenic substance or organism. "We also observed a low level expression of ARL2-SNX15, MT-RNR1, and AL591806.3 at 0 weeks during active infection, which were upregulated at 8 weeks after therapy." (PMID 37434783, 2023).
MT-RNR1 also shares sentences with these, for which no sentence is quoted: Insulin resistance (21 papers); cardiovascular disease (6); type 2 diabetes (6); metabolic disease (5); prostate carcinoma (5); osteoporosis (4); tumor (4); coronary artery disease (3); endothelial dysfunction (3); fibrosis (3); Hearing impairment (3); Alzheimer disease (2); angina (2); Hyperglycemia (2); injury (2); multiple myeloma (2); myocardial ischemia (2); sarcopenia (2); acute lung injury (1); acute myocardial infarction (1); adrenal tumors (1); adrenocortical adenoma (1); adrenocortical carcinoma (1); age-related macular degeneration (1); atrial fibrillation (1); auditory neuropathy spectrum disorder (1); benign prostatic hyperplasia (1); bladder tumor (1); breast carcinoma (1); breast tumor (1).
A further 40 diseases each share a sentence with MT-RNR1 in 1 paper.